IL5 (interleukin 5)
Diseases named in the same sentence as IL5 in open-access papers (continued):
Sharing a sentence is not in itself a finding about the gene and the disease.
osteoarthritis (2 papers, 2016 to 2023). A noninflammatory degenerative joint disease occurring chiefly in older persons, characterized by degeneration of the articular cartilage, hypertrophy of bone at the margins and changes in the synovial membrane. "The elevated serum levels for IL-5, -6, -8 and -10 prior to surgery might resemble the ongoing inflammatory reactions of the underlying osteoarthritis." (PMID 38098024, 2023).
osteoporosis (2 papers, 2023 to 2024). A condition of reduced bone mass, with decreased cortical thickness and a decrease in the number and size of the trabeculae of cancellous bone (but normal chemical composition), resulting in increased fracture incidence. "Furthermore, it has been observed that Th2 dominance is related with senile osteoporosis, implying that Th2-type cytokines such as IL-10, IL-6, IL-5, and IL-4 levels rose while Th1-type cytokines such as IL-2,IFN-γ and TNF-α reduced in patients suffering from senile osteoporosis." (PMID 38461235, 2024).
pancreatitis (2 papers, 2020 to 2023). Inflammation of the pancreas. "In addition, quantitative real-time PCR and ELISA analysis showed that the levels of IL-5, IL-18, and the chemokines eotaxin-1 and eotaxin-2 transcripts and proteins were significantly increased in cerulein-induced pancreatitis." (PMID 36969002, 2023). "A second mechanism for eosinophil recruitment in PDAC may be in response to local secretion of endogenous IL-5 from damaged acinar tissue during pancreatitis." (PMID 32552827, 2020).
pericardial effusion (2 papers, 2024 to 2025). Fluid collection within the pericardial sac, usually due to inflammation. "Furthermore, treatment could also involve monoclonal antibodies, including rituximab, which acts against CD20+ B cells, and mepolizumab, which inhibits the binding of interleukin-5 (IL-5) to its receptors expressed on eosinophils, improving cardiac function and reducing pericardial effusion." (PMID 38540269, 2024).
Periportal fibrosis (2 papers, 2012 to 2021). The presence of fibrosis affecting the interlobular stroma of liver. "The present study demonstrates a greater production of IL-4, IL-5, and IL-13 by the lymphocytes of individuals with periportal fibrosis." (PMID 33692784, 2021). "As has already been described in the literature, we found an increase of the Th2 cytokines IL-4, IL-5, and IL-13 in the group with periportal fibrosis." (PMID 33692784, 2021). "The present study showed high levels of IL-5 and TNF-α in individuals with periportal fibrosis." (PMID 23320145, 2012).
Pneumocystis pneumonia (2 papers, 2021 to 2022). "Clinicians should be aware of Pneumocystis pneumonia as a cause of refractory exacerbation of bronchial asthma during use of interleukin-5 inhibitors." (PMID 35461263, 2022). "Increased serum IL-5 levels in human and murine pneumocystosis have been reported; here we found non-significant increased IL-5 levels in BAL samples from the P. jirovecii-infected groups (HIV and non-HIV)." (PMID 34829225, 2021).
pulmonary arterial hypertension (2 papers, 2019 to 2024). Pulmonary arterial hypertension (PAH) is a group of diseases characterized by mean pulmonary artery pressure >20 mmHg and elevated pulmonary arterial resistance leading to right heart failure. "With respect to pulmonary arterial hypertension, the effect of IL-5 may be similar to that of IL-4, and the severity of pulmonary arterial muscularization correlates with IL-5–expressing T cells." (PMID 31024947, 2019). "Numerous cytokines elevated in our study, such as IL-1α, IL-4, IL-5,IL-6, IL-7, IL-8, TNF-α were previously shown to involved in VOC-related acute clinical complications such as acute chest syndrome, pulmonary hypertension, and pulmonary thrombosis." (PMID 38361924, 2024).
pulmonary haemorrhage (2 papers, 2020 to 2025). "Patients with severe pulmonary haemorrhage had significantly higher levels of IL-5, IL-6, IL-8, and IL-10." (PMID 32264832, 2020).
respiratory failure (2 papers, 2025). The significant impairment of gas exchange within the lungs resulting in hypoxia, hypercarbia, or both, to the extent that organ tissue perfusion is severely compromised. "We report the case of a patient with complete TYK2 deficiency and virally induced hypereosinophilia and respiratory failure who responded to IL-5 blockade." (PMID 40949057, 2025). "Thus, we report the case of a patient with complete TYK2 deficiency and virally induced hypereosinophilia and respiratory failure who responded to IL-5 blockade." (PMID 40949057, 2025).
respiratory syncytial virus infection (2 papers, 2014 to 2024). "Activated lung ILC2s produce large quantities of IL-5 and IL-13 that contribute to eosinophilic inflammation and mucus production following respiratory syncytial virus infection (RSV)." (PMID 38827738, 2024).
rheumatic diseases (2 papers, 2022 to 2023). "The exact molecular mechanism of IL-5 and IL-9 action in the pathogenesis of rheumatic diseases has not been well described to date." (PMID 36361964, 2022).
sarcoma (2 papers, 2023 to 2025). A usually aggressive malignant neoplasm of the soft tissue or bone. "In a previous study, where mice with IL-5 depletion in a model of sarcoma were employed, the protective role of both IL-5 and eosinophils was observed." (PMID 36376448, 2023).
sarcopenia (2 papers, 2023 to 2024). Progressive decline in muscle mass due to aging which results in decreased functional capacity of muscles. "Blood was drawn, and inflammatory biomarkers associated with Sarcopenia (IL-2, IL-4, IL-5, IL-6, IL-8, IL-10, TNF, adiponectin, leptin, resistin, BDNF, sTNFr-1 and sTNFr-2) was analysed." (PMID 37365209, 2023).
scleroderma (2 papers, 2005 to 2015). Scleroderma is a rare autoimmune connective tissue disorder characterized by abnormal hardening of the skin and, sometimes, other organs. "Recent studies with BAL in scleroderma patients have shown that a subset of them, who present more than 15% lymphocytes in BAL, or have activated, long-lived CD8+ T cells, or produce type 2 cytokines (IL-4 and IL-5) by the CD8+ TLs, present a more aggressive form of interstitial pneumonia." (PMID 16042790, 2005).
silicosis (2 papers, 2020 to 2022). Silicosis is a respiratory disease caused by breathing in (inhaling) silica dust. "Patients with asbestosis have elevated expression of IL-10 in their AMs, whereas patients with silicosis showed increased levels of IL-10, IL-4, IL-5, and IL13 in their serum." (PMID 32625201, 2020). "Patients with silicosis also had increased levels of IL-4, IL-5 IL-10, and IL-13 in their serum." (PMID 35547729, 2022). "Treg cytokines (TGF-β and IL-10) and Th2 cytokines (IL-4, IL-5, and IL-13), but not Th1 cytokines (IFN-γ, IL2, and IL-12) and pro-inflammatory cytokines (IL-1β, IL-6, and TNF-α), were found to be increased in the sera of patients with silicosis." (PMID 32625201, 2020).
squamous cell cervical cancer (2 papers, 2015 to 2020). "CSF2RB is the common beta chain receptor for the GM-CSF, IL-3, and IL-5 activation and a rare genetic variant of CSF2RB (rs16997517) is related to a decreased risk of squamous cell cervical cancer." (PMID 33042828, 2020). "By using a qRT-PCR array, we identified CD3E, IL6, VEGFA and a high IL6/IL17 ratio combined with low IL5 expression as the most prognostic factors in squamous cervical cancer." (PMID 25889974, 2015).
viral pneumonia (2 papers, 2020 to 2022). Inflammation of the lung parenchyma that is caused by a viral infection. "We observed increased Il5 lung expression in our viral pneumonia model that was associated with a significant increase in lung eosinophil numbers at day 6 post IAV infection." (PMID 35145069, 2022).
abortion (1 paper, 2025). the ending of pregnancy by removing a fetus or embryo before it can survive outside the uterus. "For instance, demonstrated that levels of IL5, IL6, IL1-ß, TNF-α, TLR4, and Tollip were significantly up-regulated in ewes affected with abortion than in resistant ones, while SOD and CAT gene patterns elicited an opposite trend." (PMID 40872670, 2025).
acral melanoma (1 paper, 2022). "IL-5 and IL-10 were positively associated with a low QOL in non-acral melanoma TNM stage II to IV." (PMID 36405903, 2022).
acute liver failure (1 paper, 2016). Rapid deterioration of liver function causing encephalopathy and coagulopathy. "Further clinical research is needed to evaluate the potentialbenefits of using IL-5 and/or IL-6 as possible biomarkers for identifying patients witha higher risk of developing severe acute liver failure." (PMID 27812602, 2016). "Our study also identified a potential role for IL-5 in the pathology ofacetaminophen-induced acute liver failure." (PMID 27812602, 2016). "It is well known that IL-5 increases liver injury by recruiting leukocytesinto the hepatic parenchyma.However, acetaminophen-induced acute liver failure is typically characterised by littleto no leukocyte infiltration in the hepatic parenchyma, which we likewise observed inthis study." (PMID 27812602, 2016).
acute pancreatitis (1 paper, 2024). An acute inflammatory process that leads to necrosis of the pancreatic parenchyma. "Serum levels of interleukin (IL)‐1β, IL‐5, IL‐6, IL‐8, IL‐10, IL‐17, and tumor necrosis factor‐α were significantly higher in the severe acute pancreatitis (SAP) group than in the non‐SAP group (p < .05)." (PMID 38411379, 2024).
adenoma (1 paper, 2010). A neoplasm arising from the epithelium. "In specific, il5+/+ mice had lung neoplastic lesions composed of 69 ± 5% AAH, 22 ± 4% adenomas, and 9 ± 2% adenocarcinomas, while il5-/- mice had 75 ± 3% AAH, 19 ± 2% adenomas, and 6 ± 1% adenocarcinomas (P > 0.05)." (PMID 20796309, 2010).
alopecia areata (1 paper, 2021). Loss of scalp and body hair involving microscopically inflammatory patchy areas. "There are limited data considering the serum level of IL-5 in patients with alopecia areata; thus, further studies are needed to confirm these preliminary observations." (PMID 34943905, 2021).
amoebic colitis (1 paper, 2019). "In addition to systemic and local induction of IL-13 and IL-5, a possible role of IL-25 can be hypothesized, as it has recently been shown in protection from amoebic colitis, acting via eosinophils and suppression of TNF-α through a new pathway of innate mucosal immune response." (PMID 31212833, 2019).
ANCA-associated vasculitis (1 paper, 2022). "Terminal complement inhibition for management of ANCA-associated vasculitis with avacopan and blockade of interleukin-5 for treatment of eosinophilic granulomatosis with polyangiitis with mepolizumab illustrate this trend." (PMID 36465944, 2022).
anisakiasis (1 paper, 2019). Infection with roundworms of the genus anisakis. "IL-4 secretion triggers IgE production by B-lymphocyte, while IL-5 involved in eosinophilic production under anisakiasis." (PMID 31849412, 2019).
ankylosing spondylitis (1 paper, 2022). An autoimmune chronic inflammatory disorder characterized by inflammation in the vertebral joints of the spine and sacroiliac joints. "Significant relationships between the IL5 rs2069812 and IL9 rs2069885 polymorphisms and response to anti-TNF treatment, expressed by the Bath Ankylosing Spondylitis Disease Activity Index (BASDAI) were observed." (PMID 36361964, 2022).
anthrax (1 paper, 2015). "Thus, cutaneous anthrax induces a broad T cell memory response characterized not only by the presence of Th1 cytokines IFNγ and TNFα, but also Th2 (IL-5 and IL-13), Th17 (IL-17/IL-22), Th22 (IL-22) and Th9 (IL-9) cytokines and a potentially regulatory IL-10 response." (PMID 26075052, 2015).
antibody deficiency (1 paper, 2020). "Significant abolishment of IL-5 of the spleen at the later infection stage, suggests a possible antibody deficiency." (PMID 33597934, 2020).
atopic march (1 paper, 2023). sequential manifestations of different allergic diseases such as eczema, asthma and rhinitis. "In particular, the T helpers 2 (Th2) subset, through its cytokine signatures made of interleukins (ILs), such as IL-4, IL-5, IL-10, and IL-13, as well as mast cells and their related histamine pathways, contribute greatly to the perpetuation and evolution of the atopic march." (PMID 36675006, 2023).
atrial fibrillation (1 paper, 2018). A disorder characterized by an electrocardiographic finding of a supraventricular arrhythmia characterized by the replacement of consistent P waves by rapid oscillations or fibrillatory waves that vary in size, shape and timing and are accompanied by an irregular ventricular response. "Conversely, lower levels of CCL3, IL-12, IL-5, IL-10, IL-13 were observed in the ZIKV-infected patient with atrial fibrillation as compared to the healthy controls." (PMID 29370812, 2018).
B-cell lymphoblastic leukemia (1 paper, 2024). "In studies, patients with B-cell lymphoblastic leukemia following CAR-T cell therapy presented elevated levels of IL-1α, IL-2, IL-3, IL-5, IL-6, IL-8 IL-10, IL-15, IFN- γ, procalcitonin, CRP, G-CSF, GM-CSF, and MCP-1, and their levels were linked to the severity of neurotoxicity." (PMID 39409959, 2024).
Buruli ulcer (1 paper, 2018). "Similarly, comparing IL-5 responses (albeit low), contacts of Buruli ulcer patients produced significantly higher IL-5 responses compared with those of patients for ATp (median 31 vs 12 pg/ml), KS C (54 vs 20 pg/ml), Atac1 (57 vs 25 pg/ml), (P < 0.05)." (PMID 30090691, 2018). "Contacts of Buruli ulcer patients produced significantly higher IFN-γ and IL-5 responses compared with those of patients to PKS domain antigens and to mycolyltransferase Ag85A of M. ulcerans." (PMID 30090691, 2018).
Cachexia (1 paper, 2017). Severe weight loss, wasting of muscle, loss of appetite, and general debility related to a chronic disease. "Despite these cytokines not presenting any difference induced by cachexia or cancer, when compared with the control group, the levels of IL5 were found to be increased in CC (p < 0.02)." (PMID 28288584, 2017).
cardiac arrest (1 paper, 2021). Cessation of breathing and/or cardiac function. "Cardiac arrest and ECPR markedly increased the plasma levels of IL-10, VEGF, leptin, TNF-α, IL-1β, IL-6, fractalkine, IL-5, IL-18, IP-10, IL-4, eotaxin, MIP-1α, IL-17α, IL-12, RANTES, G-CSF, LIX, and MCP-1." (PMID 34781966, 2021).
cervical dystonia (1 paper, 2024). "The same study also showed an increased population of B cells, monocytes, and an increased ratio of CD8+ cytotoxic cells compared to CD4+ helper cells with an increase in proinflammatory cytokines like IL-5, IL-2, PIGF, VEGF-D, IL-1ß in patients of cervical dystonia." (PMID 39651491, 2024).
cholesteatoma (1 paper, 2023). A pathologic process characterized by the proliferation of keratinizing squamous epithelium resulting in the accumulation of keratin and cells in the middle ear and/or mastoid. "Therefore, it was suspected that the formation of a specific inflammatory microenvironment in cholesteatoma may result from the upregulation of IL-5 in AMEC." (PMID 37047725, 2023).
chronic gastritis (1 paper, 2020). Inflammation of the stomach that is chronic in nature. "IL-8 leads to the migration of neutrophils and monocytes into the mucosa; the activated monocytes and dendritic cells stimulate the production of various cytokines, such as IL-4, IL-5, IL-6 and interferon-γ (IFN-γ), leading to an inflammatory reaction (chronic gastritis)." (PMID 32403331, 2020).
clostridium difficile infection (1 paper, 2025). Symptomatic infection due to the spore-forming bacterium clostridium difficile. "However, recent studies have shown that secretion of IL-5 and IL-13 from ILC2s protects mice against toxin-mediated epithelial damage during Clostridium difficile infection (CDI)." (PMID 40591723, 2025).
colonic polyps (1 paper, 2024). "Through bidirectional investigation approach, it could be inferred that certain biomarkers are more likely to be found later in the course of the illness, like bNGF, FGFBasic, GCSF, GROa, IL-13, IL-5, IL-7, MCSF, SCGFb in gastric polyps, and CTACK, MIF in colonic polyps." (PMID 39439893, 2024).
congenital toxoplasmosis (1 paper, 2020). Toxoplasma infection that is present from birth. "Thus, while the assessment of IFN-γ producing NK cells provide a putative biomarker for early prognosis of congenital toxoplasmosis, the analysis of IL-5+CD4+ T-cells upon T. gondii antigens stimulation is a potential prognostic marker of ocular involvement in infant with congenital toxoplasmosis." (PMID 33028847, 2020). "Finally, the contemporaneous analysis of T. gondii-specific IL-5+CD4+ T-cells and IFN-γ+NK-cells serve as an early prognosis tool of ocular involvement in infant with congenital toxoplasmosis." (PMID 33028847, 2020). "Furthermore, the analysis of in vitro T. gondii-specific IL5+CD4+ T-cells and IFN-γ+NK-cells displayed a high accuracy for early prognosis of ocular lesion in infant with congenital toxoplasmosis (Global Accuracy/AUC = 0.8 and 0.9, respectively)." (PMID 33028847, 2020).
dermatitis herpetiformis (1 paper, 2019). "IL-5 plays a major role in eosinophilic recruitment and has been found in the jejunal mucosa of patients with CD and dermatitis herpetiformis." (PMID 31214623, 2019).
diffuse cutaneous Leishmaniasis (1 paper, 2017). A form of LEISHMANIASIS, CUTANEOUS caused by Leishmania aethiopica in Ethiopia and Kenya, L. pifanoi in Venezuela, L. braziliensis in South America, and L. mexicana in Central America. "Patients with localized cutaneous lesion (LCL) exhibit predominant expression of iNOS, IL-1β, IL-6, MCP-1, TNF-α, and IFN-γ, while anergic diffuse cutaneous leishmaniasis (ADCL) lesions are characterized by the presence of IL-4, IL-5, IL-10, and MIP-1α and the low expression of iNOS." (PMID 28959260, 2017).
dilated cardiomyopathy (1 paper, 2021). Cardiomyopathy which is characterized by dilation and contractile dysfunction of the left and right ventricles. "The role of IL‐5 in the pathogenesis of DCMi was to mobilize IL‐4‐producing eosinophils into the myocardium, which then in turn were responsible for the dilated cardiomyopathy." (PMID 34773379, 2021).
echinococcosis (1 paper, 2024). A parasitic infection caused by tapeworm larvae of Echinococcus. "Interestingly, unlike the type of T cell response generated in chronic patients with echinococcosis, we found that primed splenocytes with HF-stimulated BMDCs blocked the induction of cytokines related to Th2 profile (il-4, il5, il-13)." (PMID 38817444, 2024).
egg allergy (1 paper, 2016). A food allergy that is an allergy or hypersensitivity to dietary substances from the yolk or whites of eggs, causing an overreaction of the immune system which may lead to severe physical symptoms. "Using a combination of differential gene expression and multiplex cytokine measurement, we observed that egg allergy was associated with IL-9, IL-5, and TNFα expression and secretion, as well as expression of CEACAM1, and CISH." (PMID 27788149, 2016).
enteritis (1 paper, 2021). Inflammation of the small intestine. "In addition, we investigated the change in the proportion of Th2 cytokines in the intestinal mucosa of mice with DSS‐induced enteritis using ELISA, finding that the mice with DSS‐induced enteritis displayed significantly higher IL‐4, IL‐5 and IL‐13 levels than the control group." (PMID 33569850, 2021).
eosinophilic gastrointestinal disease (1 paper, 2018). "IL-5-producing Tpath2 cells have been detected in the PBMCs of patients with eosinophilic gastrointestinal disease." (PMID 29951134, 2018).
fertility disorders (1 paper, 2009). "In contrast, IL-1β, IL-4, IL-5, IL-6 and IL-10 mRNA expression levels were significantly higher (P < 0.05) in cells obtained from CT-positive women with fertility disorders compared to other two groups." (PMID 19397832, 2009). "In contrast, IL-1 Beta, IL-4, IL-5, IL-6 and IL-10 levels were found to be higher in CT-positive women with fertility disorders compared to CT-positive fertile women and controls (P < 0.05)." (PMID 19397832, 2009).